CD4 (CD4 molecule)
Diseases named in the same sentence as CD4 in open-access papers (continued):
Sharing a sentence is not in itself a finding about the gene and the disease.
Sepsis (continued). "In the immediate aftermath of sepsis onset, CD4 and CD8 T cells often demonstrate a depleted state accompanied by significant functional impairments." (PMID 38281996, 2024). "Data from a murine model of sepsis showed blunted differentiation and class-switching of B cells in septic mice compared to controls, with reduced expansion and differentiation of CD4+ TFH cells following immunisation." (PMID 38197178, 2024). "It was recently found that the mTOR pathway played vital role in regulation of CD4+ T-cell apoptosis through autophagic lysosomal fusion dysfunction during sepsis." (PMID 39104530, 2024). "Further, it has been proven that CD4+T is involved in the activation of early-responding immune cells in sepsis." (PMID 38545097, 2024). "The results are supported by other recent studies that found a significantly reduced number of CD4+ cells in sepsis patients." (PMID 39064603, 2024). "Alcohol-drinking WT and Cd4-CreERT2Ctla4fl/fl mice were then monitored for survival following sepsis." (PMID 38226924, 2024). "The proportions of memory B cells and naive CD4+ T cells were lower in sepsis than in normal samples, while monocytes, neutrophils, and macrophages were higher in sepsis samples." (PMID 38894720, 2024). "In order to elucidate the function of CTLA4 in CD4+ T cell dysfunction during sepsis, we employed western blotting to quantify CTLA4 expression, which revealed that CTLA4 was considerably accumulated in septic mice." (PMID 39104632, 2024). "As far as we know, the current study is one of the earliest studies correlating CD4+ T lymphocyte counts to a prognostic value of sepsis patients using the Sepsis-3 criterion." (PMID 39290582, 2024). "This review will specifically focus on how sepsis destabilises the adaptive immune system, with a closer examination on how B cells and CD4+ TFH cells are affected by sepsis and the corresponding impact on humoral immunity." (PMID 38197178, 2024). "Their findings revealed that the CD4+ T lymphocyte subgroup differentiation rate was substantially lower in sepsis patients administered with oral vitamin D compared to a healthy control group (P < .01)." (PMID 39465765, 2024). "ROC curve analysis showed that 0.2810 (×109/L) of CD4+ T lymphocyte counts was the optimal threshold for predicting 28-day mortality in patients with sepsis." (PMID 39290582, 2024). "Among CD4+ cells, the production of Th1- and Th2-related cytokines decreases both during and after sepsis." (PMID 38474403, 2024). "Previous literatures have suggested that activated memory CD4+ T cells are involved in modulating the function of neutrophils, fostering bactericidal functions, and improving animal survival during sepsis." (PMID 38912048, 2024). "TK exerts both preventative and therapeutic effects in sepsis by markedly suppressing pro-inflammatory cytokine expression, modulating immune responses, and reducing excessive activation of CD4+ and CD8+ T cells." (PMID 39282561, 2024). "Splenocytes harvested from deceased patients with sepsis demonstrate reduced numbers of CD4+ and CD8+ lymphocytes that emanate from substantial apoptosis." (PMID 39726536, 2024). "In this study, we provide evidence that, despite a reduction in the number of CD4+ T cells in the late stage of sepsis, there is a notable upregulation in the proportion of Tregs." (PMID 38888975, 2024). "The subsequent principal component analysis showed that the immune potential indicators (CD4+ T-cell count, HLA-DR+ monocytes (%), and mDCs (%)) and anti-inflammatory cytokine IL-1ra were the most important variables in HCs and sepsis patients, respectively." (PMID 38707899, 2024). "In our study, SAI was associated with a higher 28-day morality rate for patients with sepsis, and CTLA-4 MFI on CD4+ T lymphocytes was an independent risk factor for the incidence of SAI." (PMID 39104530, 2024).
Sepsis (continued). "The decrease in the number and dysfunction of CD4+ T lymphocytes is crucial to the immunosuppressed state of sepsis, in turn affecting the development and prognosis of sepsis." (PMID 39439897, 2024). "Instead, their results indicated that TIM-3 exhibits a relatively strong binding affinity for HMGB1, suggesting its potential as a receptor for HMGB1 in TIM-3+ CD4+ T cells during sepsis." (PMID 38576606, 2024). "In line with previous studies, it was demonstrated that CTLA-4 expression is upregulated on CD4+ in sepsis." (PMID 39104632, 2024). "The normal CD4 to CD8 T cells ratio (2:1) observed in sham animals was reduced to 1:1 in both WT and KO mice after sepsis, suggesting that sepsis alters the proportion of CD4 and CD8 T cells in the spleen." (PMID 38720893, 2024). "Patients with sepsis, especially those with severe sepsis and septic shock, have significantly elevated levels of PD-1 expression in CD4 + or CD8 + T cells and PD-L1 expression in monocytes." (PMID 37776443, 2024). "CD4+ T cells are the mainstay of the body's immune system, and the depletion of CD4+ T cells in sepsis is of great concern." (PMID 39104632, 2024). "In comparison with trauma patients and healthy volunteers, PD‐1 expression is increased on monocytes and CD4 + T cells after sepsis." (PMID 38270311, 2024). "Consistent with prior single-cell analysis results, our research demonstrated that sepsis advancement is associated with a decrease in lymphocytes, characterized by lower counts of CD8 and CD4 T cells, B cells, and NK cells." (PMID 39763654, 2024). "The LIPT1-T cells CD4 memory resting was the most positively correlated DECuGs–immunocyte pair (r = 0.65, P-value<0.001), a higher expression level of LIPT1 and a higher infiltration of T cells CD4 memory resting cells in sepsis." (PMID 38495196, 2024). "TIGIT deficiency enhanced CD4+ T cell effector function and facilitated bacterial clearance during CLP induced-sepsis, resulting in decreased organ injury." (PMID 38545097, 2024). "Further studies are required to determine if this is the case for sepsis, but also to expand our knowledge of CD4+ TFH cell-mediated humoral immunity in the context of bacterial infections and sepsis." (PMID 38197178, 2024). "The mentioned findings indicate that aberrant CD4+ T cell proliferation and inflammation-related dysregulation occurred during sepsis." (PMID 39104632, 2024). "Conversely, “T cells CD4 memory activated,” “NK cells activated,” and “Monocytes” were down-regulated in sepsis samples." (PMID 39029061, 2024). "Although many indicators like M-MDSCs (%), CD4+ T-cell count, and Tfh17 cells (%) differed significantly between sepsis and bacteremia patients, using a single indicator for distinguishing these two conditions was unsatisfactory." (PMID 38707899, 2024). "Excessive apoptosis of splenic CD4+, CD8+ T, and B cells, coupled with reduced autophagy in CD4+ T cells, has been observed in patients with sepsis, thereby accelerating acquired immunodeficiency." (PMID 39720718, 2024). "The AUC of CTLA-4 MFI for the prediction of 28-day mortality of all sepsis patients was 0.906, which was better than those for lymphocyte and CD4+ T lymphocyte counts (AUC: 0.650 and 0.693." (PMID 39104530, 2024). "The number of CD4 T cells decreased after sepsis in both WT and KO mice; however, this reduction was less pronounced in the KO mice." (PMID 38720893, 2024). "Chronic myeloid leukemia had the highest correlation value with the T-cell CD4 memory resting/macrophage M1 ratio (R = 0.60, P < 0.01), and it was down-regulated in sepsis." (PMID 38053180, 2023). "Similar to the effect of intramuscular CYT107, intravenous administration of CYT107 reversed the profound sepsis-induced loss in CD4+ and CD8+ T cells in sepsis." (PMID 36906875, 2023). "We now find that overall kidney immune cell composition in early experimental sepsis (first 24 hours) is characterized by dominant infiltration of CD4+ and CD8+ T cells, and NK1.1+ cells." (PMID 37036003, 2023).
Sepsis (continued). "Consistent with CD4+ Tcm cell dynamics, we observed a sepsis-specific decrease in CD8+ Tcm cells (scrambled control vs. sham: P < 0.05; anti–miR-93-5p vs. control: P < 0.05, scrambled control vs. control: P < 0.01)." (PMID 37261908, 2023). "Animal research has shown that mice with increased gut microbiome α-diversity have increased chance of surviving from sepsis because of their increased CD4+ T cell response." (PMID 37845615, 2023). "The present study is focused on exosomal function, so EVs were extracted from the serum of patients with sepsis-induced lung injury (and control subjects) or cultured primary human CD4+ T cells treated with LPS." (PMID 36959535, 2023). "Mucosa-associated lymphoid tissue lymphoma translocation protein 1 amplifies multiple organ injury, inflammation, oxidative stress, and imbalance of macrophages and CD4+ T cells by activating the NF-κB pathway in sepsis." (PMID 36960276, 2023). "During sepsis, CD4+ T cells are activated in response to antigen presentation by dendritic cells or monocytes, releasing immunomodulators and coordinating cytotoxic CD8+ T cells." (PMID 37346225, 2023). "CD3+CD4+ T cells significantly increased early in sepsis (P<0,001), and their levels were restored 120 days after infection at similar levels to surgery controls." (PMID 38094297, 2023). "In contrast, the proportions of CD8 + T cells, naïve CD4 + T cells, resting memory CD4 + T cells, acting memory CD4 + T cells, resting NK cells and activated NK cells in sepsis patients were lower than those in healthy controls." (PMID 36781867, 2023). "There is growing evidence that CD4 + CD25 + Foxp3 + Tregs play an active role in reducing sepsis-induced inflammation through TGF-β-dependent and TGF-β-independent pathways." (PMID 36816800, 2023). "Other studies have shown that CD4+ T cells decrease only in septic survivors after 6 days of sepsis development compared to control groups." (PMID 38094297, 2023). "CD4+ T cells are important lymphocytes that play crucial roles in modulating immune responses during sepsis and lung injury." (PMID 36959535, 2023). "Prior research indicates that sepsis prompts apoptosis in immune cells, especially in the spleen, resulting in a marked reduction of CD4+ and CD8+ T cells." (PMID 38259439, 2023). "In studying experimental sepsis, it was found that T cell proportions were also affected, such as CD4+ as well as CD8+ T cells, which were major components of the immune dysfunction of sepsis." (PMID 37647455, 2023). "On the contrary, sepsis leads to the reduction in CD4+ T cells, γδ T cells, CD8+ T cells, B cells, NK cells and dendritic cells by accelerating apoptosis." (PMID 37701780, 2023). "Colorectal cancer had the highest correlation with the T-cell CD4 memory resting/mast-cell resting ratio (R = 0.60, P < 0.01), and it was down-regulated in sepsis." (PMID 38053180, 2023). "IFNγ also reduces CD4 + T cell inhibitory receptor expression and systemic inflammation in septic mice; however, the mechanism by which IFNγ exerts immune regulation in sepsis is unclear." (PMID 37434129, 2023). "How CD4+ T cells affect immune response and the whole process of pathogenesis in sepsis-induced lung injury remains to be elucidated." (PMID 36959535, 2023). "Reductions in CD4+ Tcm cells in spleens from the CLP-induced sepsis mouse model have been reported previously." (PMID 37261908, 2023). "In patients with liver cirrhosis and sepsis, GM-CSF therapy regulates the ratio of myeloid-derived suppressor cells and Tregs and improves immune function of CD4+ T cells." (PMID 37629199, 2023). "Taken together, these results demonstrate the importance of CD4+ T cell function during sepsis, which positively correlates with the increase of P2X7 receptor in these cells." (PMID 38094297, 2023).
Sepsis (continued). "Our data reveal increased p-ITK protein levels in circulating CD4+ T cells and ITK protein levels in the cerebral cortex, which are associated with sepsis-mediated neuroinflammation and depression-like symptoms." (PMID 37175808, 2023). "This sepsis-induced lymphopenia is broad-based and includes CD4+ and CD8+ T cells, B cells, and natural killer cells." (PMID 36906875, 2023). "Accordingly, we also observed a decrease in the expression of CD4 during sepsis, which is essential for T cell recognition by the antigen-presenting cell." (PMID 38094297, 2023). "In a report from 19 countries, HIV-infected individuals with low CD4 cell counts developed necrotizing skin lesions, nodular lung involvement, secondary infections, sepsis, and fatal outcomes." (PMID 37367191, 2023). "Treatment with the ITK inhibitor caused a downregulation in the p-ITK+ CD4+ T cells and ITK levels in the CNS of sepsis survivor mice." (PMID 37175808, 2023). "In sepsis and burn patients, Th2 cells, Th17 cells, Tfh cells, iTregs and CD4_T cells were highly positively correlated." (PMID 37060578, 2023). "In mice with sepsis induced by cecal ligation and puncture, EVs derived from CD4+ T cells also promoted tissue damage, oxidative stress, and inflammation in the lungs." (PMID 36959535, 2023). "Our data show that IL-10 and Foxp3 are elevated in CD4+ T cells in the periphery of sepsis survivor mice as depicted by the % of IL-10+ CD4+ T cells and Foxp3+ CD4+ T cells." (PMID 37175808, 2023). "This work establishes unambiguously that systemic hyperinflammtion upon infection was aggrevated by the loss of CD4+ T cells, that unleashed the restrains of MHC II/TLR4 inflammatory "signalosome" for cytokine storm or cytokine release syndrome in sepsis." (PMID 37332010, 2023). "We found T-cell gamma delta/B-cell memory and T-cell CD4 memory resting/B-cell memory ratios were up-regulated in sepsis." (PMID 38053180, 2023). "Previous studies have shown that B and CD4+ T cells undergo apoptosis during sepsis, leading to an increase in the proportion of cytotoxic NK and CD8+ T cells." (PMID 38094297, 2023). "In sepsis, large quantities of Cluster of Differentiation 4 (CD4+) and CD8+ T lymphocytes, B lymphocytes, and dendritic cells (DCs) are lost due to apoptosis." (PMID 37681852, 2023). "Previously, it has been reported that CD3+ and CD4+ T cell count were independent prognostic factors for death in older adults with severe community-acquired pneumonia and sepsis." (PMID 38249419, 2023). "Melanogenesis had the highest correlation with the T-cell CD4 memory resting/macrophage M2 ratio (R = 0.60, P < 0.01), and it was down-regulated in sepsis." (PMID 38053180, 2023). "CD4+ T cells were more prone to sepsis-induced apoptosis, shown by reduced ratios of CD4/CD8 T cell counts in the thymus and spleen, as compared to the sham mice." (PMID 37332010, 2023). "Results determined that the decrease in CD4 T cells was even more pronounced in sepsis patients that were classified as immune paralysis." (PMID 37317092, 2023). "The violin diagram indicated that the infiltration of activated dendritic cells, activated CD4 T cells, macrophages, mast cells, neutrophils, NK cells, T helper 17 cells, and regulatory T cells was higher in sepsis patients than in controls." (PMID 37139640, 2023). "In a CLP mouse model of sepsis, T cell apoptosis was induced, while autophagy in CD4+ spleen cells and CD8+ spleen cells was downregulated." (PMID 38020710, 2023). "M63, the most significantly upregulated module in sepsis, was annotated as endothelial and CD4+ T cell (–)." (PMID 38071387, 2023). "IL-7 immunotherapy improved clinical symptoms, cleared the fungus, reversed lymphopenia, and reversed the profound loss of CD4+ and CD8+ T cells induced by sepsis." (PMID 38114466, 2023). "Our data showed an increased expression of p-ITK and its downstream targets in CD4+ T cells and the CNS in mice with sepsis." (PMID 37175808, 2023).
Sepsis (continued). "Progesterone mediated oocyte maturation had the highest correlation with the T-cell CD4 memory resting/eosinophil ratio (R = 0.65, P < 0.01), and it was down-regulated in sepsis." (PMID 38053180, 2023). "We found that the cell counts of CD4 T cells were highest in sham group while lowest in sepsis group." (PMID 37113759, 2023). "In the event of sepsis, naive CD4+ T cells differentiate into different cell phenotypes, namely, Th1, Th2 and Th17, after homologous antigen (Ag) expression by antigen‐presenting cells (APCs) and Tregs." (PMID 37060578, 2023). "The dysregulation of immune cells, including macrophages and CD4+ T cells, is also a vital pathogenesis of sepsis." (PMID 36960276, 2023). "Impaired CD4 T cell function after sepsis, characterized by decreased cytokine secretion and increased expression of inhibitory receptors, restricts the assistance provided to other immune cells." (PMID 38114466, 2023). "To further elucidate the action of the PKC/NOX4 pathway downstream of LPS-treated CD4+ T-cell-derived EVs in sepsis-induced lung injury, we directed our attention to CLP-induced sepsis in mice." (PMID 36959535, 2023). "Our study found that the proportions of CD4+ as well as CD8+ T cells induced by sepsis decreased significantly, while Emo treatment greatly reduced this reduction effect." (PMID 37647455, 2023). "Median CD4 count ranged from 40 cells/mm3 in a Zambian trial that recruited patients with suspected severe sepsis during 2012, to 227 cells/mm3 in a trial that recruited all PLHIV admitted to general medical wards in Malawi and South Africa during 2015–2017." (PMID 36963024, 2023). "The NF-κB pathway is able to regulate cell apoptosis, inflammation, oxidative stress, and polarization of macrophages and CD4+ T cells, which are critical mechanisms of sepsis." (PMID 36960276, 2023). "Our study showed an increased activation of ITK in CD4+ T cells as reflected by an increased % of p-ITK+ CD4+ T cells in the periphery of sepsis survivor mice." (PMID 37175808, 2023). "The VEGF signaling pathway had the highest correlation with the T-cell CD4 memory resting/eosinophil ratio (R = 0.61, P < 0.01), and it was down-regulated in sepsis." (PMID 38053180, 2023). "We found that eosinophil/B.cell.memory ratio was up-regulated in sepsis, whereas T.cell.CD4.non.regulatory/T.cell.CD8 was down-regulated in sepsis." (PMID 38053180, 2023). "To investigate the activity and regulation of ribophagy in T lymphocytes during sepsis, we stimulated splenic CD4+ T lymphocytes and Jurkat cells with LPS at 500 ng/ml for 6, 12, 24, 48 and 72 h." (PMID 36873287, 2023). "Taken together, these data suggest that EVs derived from the serum of patients with sepsis-induced lung injury and LPS-treated CD4+ T cells promoted sepsis-induced lung injury." (PMID 36959535, 2023). "It has been reported that the T-cell CD4 naïve number decreases and its function weakens, and its ability to respond to pathogens decreases in sepsis." (PMID 38053180, 2023). "A significant decrease in lymphocytes (especially CD4 T lymphocytes) was well characterized in sepsis." (PMID 37671148, 2023). "Studies have found that recurrent sepsis can deplete human CD4+ T cells, thereby changing the prognosis of patients." (PMID 37449204, 2023). "Similar to other cell subsets, the percentage of CD4++CD25+CD127-/low cells with P2X7 expression was increased in sepsis (P<0,01**), and positively correlated with the expression of the P2X7 receptor in monocytes (P=0,0233*)." (PMID 38094297, 2023). "Small cell lung cancer had the highest correlation with the T-cell CD4 memory resting/macrophage M1 ratio (R = 0.65, P < 0.01), and it was down-regulated in sepsis." (PMID 38053180, 2023). "The analysis indicated that Activated CD4 T cell, Activated dendritic cell, Memory B cell, and Regulatory T cell were more significantly expressed in sepsis cluster 1 (P<0.05)." (PMID 38332910, 2023).